L1CAM (L1 cell adhesion molecule)
Diseases named in the same sentence as L1CAM in open-access papers (continued):
Sharing a sentence is not in itself a finding about the gene and the disease.
melanoma (50 papers, 2009 to 2025). A malignant, usually aggressive tumor composed of atypical, neoplastic melanocytes. "We show that knocking out α-syn in melanoma cell lines and low expression of α-syn in a neuroblastoma cell line cause significant decreases in L1CAM compared to control cells that express α-syn." (PMID 37286800, 2023). "In the melanoma lines, loss of α-syn expression resulted in significant decreases in the expression of L1CAM and N-cadherin and concomitant significant decreases in motility." (PMID 37286800, 2023). "L1CAM expression in primary melanoma was significantly associated with HIF-1α expression (p < 0.0001) and sentinel lymph node metastasis (p = 0.011)." (PMID 36142656, 2022). "Several members of the IgSF, including MCAM (CD146), NCAM (CD56), ALCAM (CD166), and L1-CAM (CD171) have been associated with metastasis in several cancers such as melanoma." (PMID 34207884, 2021). "L1-CAM is another cell adhesion molecule, and its over-expression was associated with melanoma metastasis." (PMID 34207884, 2021). "The transcription of several genes encoding factors implicated in melanoma growth, including L1CAM, can be modulated by β-catenin/TCF-LEF." (PMID 30909648, 2019). "Significantly, L1-CAM has been implicated in melanoma progression, and is a key positive modulator of metastasis in both wild-type and BRAFV600E melanomas." (PMID 30909648, 2019). "L1CAM is also reported to be associated with the Wnt/b-catenin pathway, both as target in colorectal carcinoma but also as upstream regulator in melanoma and breast cancer." (PMID 31455004, 2019). "Obviously, a considerable reduction in L1CAM causes a serious disruption of the highly complex intra- and/or intercellular signaling network determining the melanoma cells’ metastatic potential." (PMID 29432466, 2018). "We found that metastatic L1CAM possesses only α2-6-linked sialic acid and the loss of α2-3-linked sialic acid in L1CAM is a phenomenon observed during the transition of melanoma cells from VGP to a metastatic stage." (PMID 22544341, 2013). "The altered reactivity of primary and metastatic L1CAM with MAA showed the presence of α2-3-linked sialic acid only in L1CAM from primary melanoma." (PMID 22544341, 2013). "The loss of α2-3-linked sialic acid in L1CAM is a phenomenon observed during the transition of melanoma cells from VGP to a metastatic stage." (PMID 22544341, 2013). "Combined treatment with S. pneumoniae sialidase and mAb showed an additional effect, suggesting the important role of α2-3-linked sialic acid in the L1CAM molecule in the invasive behaviour of primary melanoma cells." (PMID 22544341, 2013). "We analysed the N-linked glycans of L1CAM from different stages of melanoma progression, using high-performance liquid chromatography combined with exoglycosidase sequencing, matrix-assisted laser desorption/ionisation time-of-flight mass spectrometry, and lectin probes." (PMID 22544341, 2013). "We wanted to find out whether that is a more general hallmark of L1CAM glycosylation during the transition of melanoma cells from the vertical growth phase to a metastatic stage." (PMID 22544341, 2013). "To answer this we precipitated glycoproteins from four primary and three metastatic cell lines using MAA and SNA lectins, and determined that the loss of α2-3-linked sialic acid in L1CAM is a phenomenon observed during the transition of melanoma cells from VGP to a metastatic stage." (PMID 22544341, 2013). "The fucosylation of the L1 cell adhesion molecule (L1CAM) by AR-activated FUT4 further promotes metastatic progression in melanoma." (PMID 40564107, 2025). "We previously reported increased lysosomal degradation of the cell-surface proteins TFR1 and L1CAM in SK-MEL-28 SNCA-KO melanoma cells compared to control cells." (PMID 40521809, 2025).
melanoma (continued). "This is the case of the cell adhesion molecule L1CAM, which orchestrates neuronal axonal growth and guidance, including that of midbrain DA neurons, while also promoting melanoma cell mobility, invasion and migration." (PMID 41460324, 2025). "Here the authors show that androgen-activated AR transcriptionally upregulates fucosyltransferase 4, which fucosylates L1CAM and promotes melanoma invasiveness by disrupting adherens junctions." (PMID 38326303, 2024). "Glycobiological studies on fucosylated-L1CAM are needed to map the fucosylation sites, dissect their effects on L1CAM functions, and assess their contributions to androgen-driven melanoma metastasis." (PMID 38326303, 2024). "Together, these findings support the role of AR in driving aggressive melanoma pathogenesis via fucosylation of L1CAM and abrogation of AJ complexes in male patients." (PMID 38326303, 2024). "Core fucosylation of L1CAM via FUT8 was previously reported to impair L1CAM cleavage, stabilizing it on the cell surface and enhancing the ability of L1CAM to support melanoma invasion." (PMID 38326303, 2024). "We next sought to delineate the functional contributions of L1CAM to AR-FUT4-regulated melanoma biology by generating melanoma cells that were simultaneously modified for FUT4 (overexpression) and L1CAM (knockdown)." (PMID 38326303, 2024). "Whereas manipulation of either or both FUT4 and L1CAM did not impact melanoma viability regardless of ARi treatment, the depletion of L1CAM abrogated DHT or FUT4-induced melanoma motility." (PMID 38326303, 2024). "Here, we revealed that AR-FUT4-mediated terminal fucosylation of L1CAM also confers metastatic behavior to melanoma cells." (PMID 38326303, 2024). "We propose that α-syn is pro-survival to melanoma (and possibly neuroblastoma) because it promotes the intracellular trafficking of L1CAM to the plasma membrane." (PMID 37286800, 2023). "Our interpretation of these findings is that α-syn is a pro-survival factor in melanoma because it acts post-translationally to maintain a high levels of L1CAM and in turn high levels of motility." (PMID 37286800, 2023). "We propose that α-syn is pro-survival to melanoma (and likely neuroblastoma) because it promotes the efficient vesicular trafficking of L1CAM to the plasma membrane, which in turn promotes invasion, migration, and motility." (PMID 37286800, 2023). "L1CAM has been shown to have a critical role in metastatic progression in multiple tumor types including glioblastoma, melanoma, breast, renal, and colorectal cancers." (PMID 36509990, 2022). "Knockdown of cellular L1CAM reduced melanoma cell migration and abrogated the chemoresistance against cisplatin." (PMID 36142656, 2022). "A later study, using a xenograft mouse model of human melanoma, showed that the knockdown of L1CAM reduced the melanoma cell’s ability to metastasise." (PMID 34439879, 2021). "For example, FUT8-mediated core fucosylation alters L1CAM proteolytic cleavage, which facilitates melanoma cell invasion and tumor dissemination." (PMID 33976130, 2021). "At present, L1CAM protein has been studied in evaluating the malignancy and prognosis of ovarian, endometrial and melanoma tumors 18,25,32,33." (PMID 32742486, 2020). "The therapeutic effects of anti-L1CAM antibodies were also assessed in melanoma and pancreatic carcinoma." (PMID 32429448, 2020). "FER-depleted melanoma cells exhibit impaired Wnt/β-catenin pathway activity, as well as multiple proteomic changes, which include decreased abundance of L1-cell adhesion molecule (L1-CAM)." (PMID 30909648, 2019).
melanoma (continued). "We now demonstrate that FER promotes L1-CAM expression and metastasis in melanoma cells, placing FER as a potential target in this tumor type." (PMID 30909648, 2019). "Recently, L1CAM has been suggested to be a key mediator of the pro-metastatic role played by core fucosylation by FUT8 in melanoma." (PMID 29432466, 2018). "Summarized, in a melanoma xenograft model, L1CAM knockdown reduced lung metastasis by the factor 7.26." (PMID 29432466, 2018). "High L1CAM expression in melanoma can obviously modulate the network of EMT gene expression in a pro-metastatic way with a strong influence on TGFβ signaling." (PMID 29432466, 2018). "Core-fucosylation (α-1,6 fucosylation) catalyzed by FUT8 is highly elevated in metastatic melanoma, and promotes melanoma progression and metastasis by regulating L1CAM cleavage and L1CAM-mediated invasion." (PMID 29924834, 2018). "Further, L1CAM promotes tumor progression and metastasis in melanoma and ovarian, gastric, lung, and pancreatic cancers, where its presence is associated with a poor prognosis." (PMID 29615539, 2018). "This reduction is probably not caused by a less aggressively growing primary tumors, a change in survival time or a decrease in CTC number, as all this parameters remain unaltered by L1CAM knockdown in the human melanoma cells." (PMID 29432466, 2018). "Taken together, these data make L1CAM a highly interesting therapeutic target to prevent further metastatic spread in melanoma patients." (PMID 29432466, 2018). "In a spontaneous metastasis xenograft model of human melanoma a shRNA mediated knockdown of L1CAM more than sevenfold reduced the number of lung metastases after the induction of subcutaneous tumors for two human melanoma cell lines (MeWo, MV3)." (PMID 29432466, 2018). "Summarized, L1CAM knockdown in the originally L1CAM high human melanoma cell line MeWo led to a reduced expression of EMT-related genes in the respective xenograft tumors (which also displayed reduced metastatic potential)." (PMID 29432466, 2018). "In melanoma cells, for example, the αvβ3 integrin establishes heterophilic interactions with L1CAM in the endothelium, thus enhancing the migration of tumor cells across the vascular barrier." (PMID 28134764, 2017). "Thereafter, vascular expression of L1CAM was detected in melanoma, smooth muscle tumors, and neural tumors." (PMID 28134764, 2017). "In functional tests we showed the importance of L1CAM glycans in the migratory and invasive behaviour of melanoma cells." (PMID 22544341, 2013). "HPLC data for the 2AB-labelled glycan pool of L1CAM from metastatic melanoma cells were analysed as was done for the primary analogue." (PMID 22544341, 2013). "Since cancer cells shed the L1CAM ectodomain into circulation, the NeuGcAcGalβ1-4Galβ1-4 xeno-autoantigen potentially gives us a novel serum biomarker for early detection of melanoma." (PMID 22544341, 2013). "The main aim of this study was to determine the N-glycosylation pattern of the L1CAM molecule at different stages of melanoma progression and to evaluate the effect of these glycans on melanoma cell behaviour." (PMID 22544341, 2013). "L1CAM from primary melanoma cells possessed 5.5 % core fucosylated structures and 5.5 % Lex structures." (PMID 22544341, 2013). "Our findings confirm the previous observation that L1CAM affects migratory behaviour and invasiveness more strongly in metastatic than in primary melanoma cells." (PMID 22544341, 2013).
melanoma (continued). "The wound healing studies were intended to evaluate the role of cell surface oligosaccharides and L1CAM oligosaccharides in the migratory behaviour of melanoma cells." (PMID 22544341, 2013). "In melanoma the expression of L1CAM occurs in a stage-dependent manner; L1CAM is expressed in primary melanomas and cutaneous metastases and not in melanocytic nevi and melanocytes." (PMID 22544341, 2013). "Further work should more precisely determine the glycosylation pattern of L1CAM in different stages of melanoma progression, especially the diversity in sialic acid content." (PMID 22544341, 2013). "Here we have shown that L1CAM protein can also carry an acetylated form of sialic acid in human melanoma." (PMID 22544341, 2013). "L1CAM, a member of immunoglobulin-like CAMs, was first reported to be involved in human cancers by investigating its expression in B16 melanoma cells." (PMID 22888955, 2012). "Similar reports have indicated that upregulation of ALCAM and L1CAM mediates homophilic cell-cell cohesion in invading melanoma and colorectal carcinoma, respectively." (PMID 22272201, 2012). "In our previous study we demonstrated that ADAM10 is involved in the shedding of L1-CAM, a neural cell adhesion molecule known to be overexpressed in different types of cancer including melanoma." (PMID 21876729, 2011). "In melanoma cells with elevated expression of α-syn, there is robust anterograde membrane traffic that results in the delivery of key adhesion molecules, which control invasion and migration, to the plasma membrane, i.e. L1CAM and CD81 and others." (PMID 40521809, 2025). "This was associated with the downregulation of adhesion molecules such as L1CAM and N-cadherin, indicating that α-syn may support melanoma progression by promoting L1CAM and N-cadherin recycling to the plasma membrane." (PMID 41460324, 2025). "Melanoma cells may use L1CAM to bind αvβ3 on endothelial cells to promote transendothelial migration." (PMID 31455004, 2019). "Interestingly, this decrease was observed for melanoma cells with originally high L1CAM expression as well as for melanoma cells with initially low L1CAM expression." (PMID 29432466, 2018). "L1Cam could be an especially interesting target, as even patients with L1CAM low melanoma could profit from anti-L1CAM treatment." (PMID 29432466, 2018). "Aim of this study was to investigate whether L1CAM plays this functional role in melanoma metastasis in a model comprising the whole metastatic cascade." (PMID 29432466, 2018). "The fact that the melanoma cells were not able to fully compensate the partial loss of L1CAM makes this CAM a highly interesting therapeutic target to prevent further metastatic spread in patients." (PMID 29432466, 2018). "According to our data from this study, L1CAM plays a functional role in melanoma metastasis and can influence the expression of “EMT” genes, however, this role appears to be in later stages of metastasis rather than in earlier stages as would be expected of a “classic” EMT molecule." (PMID 29432466, 2018). "Although others have reported that, during metastasis, melanoma cells undergo transendothelial cell migration through a mechanism involving an interaction between integrin αvβ3 on melanoma cells and L1CAM on ECs, it should be noted that GBM tumors rarely metastasize outside of the brain." (PMID 27270311, 2016). "Indeed, previous works described binding of αvβ3 integrin as expressed by melanoma cells to blood vascular endothelium via endothelium-expressed L1CAM." (PMID 24884715, 2014).
melanoma (continued). "Next we examined whether cell surface oligosaccharides and L1CAM oligosaccharides could influence the invasiveness of melanoma cell lines in a matrigel invasion assay." (PMID 22544341, 2013). "L1CAM was initially identified in neural cells, but its expression has also been seen in some other normal tissues and in several types of human carcinomas and melanomas." (PMID 22544341, 2013). "L1CAM from VGP melanoma cells and metastatic cells showed quite similar glycosylation patterns." (PMID 22544341, 2013). "As the results, L1CAM expression was observed in lung cancer cell lines, gallbladder carcinomas, colon cancer, pancreatic cancer, renal cell cancer, gliomas, ovarian carcinomas, endometrial carcinomas, and melanomas." (PMID 22888955, 2012). "Therefore, inhibition of L1CAM represents another promising target against melanoma." (PMID 39820173, 2025). "Herein, we found here that knocking out SNCA significantly reduces the level of L1CAM relative to control cells that express α-syn, and the decreased level of this adhesion protein likely contributes to the reduction in cell motility in two melanoma cell lines and one neuroblastoma cell line." (PMID 37286800, 2023). "Thus, inhibition of L1CAM is another promising anti-melanoma target." (PMID 34439879, 2021). "L1CAM of primary melanoma but not L1CAM of metastatic melanoma possesses α2-3-linked sialic acid." (PMID 22544341, 2013). "As a methodology, SFD is able to reveal well-known proteins in melanoma exosomes that are immune-related and are also surface-expressed proteins, such as CD26 (DPP4), CD44, CALR, B7-H3 (CD276), CSF1, ICAM1, L1CAM, MICB, APOH, TIMP1, and CD39." (PMID 40805206, 2025). "Integrated proteomics analysis identified L1CAM as a key downstream effector fucosylated by FUT4, which is required for AR-FUT4-promoted melanoma metastasis." (PMID 38326303, 2024). "Our results highlight the relevance of Ezrin, L1CAM and HIF-1α as prognostic markers in melanoma patients." (PMID 36142656, 2022). "In melanoma, up regulation of FUT8 was identified as a driving factor of metastasis via reducing cleavage of fucosylated adhesion molecule, L1CAM." (PMID 34703796, 2021). "Melanoma cells themselves can express melanocyte adhesion molecule (MCAM)/MUC18, L1-CAM, α4β1-integrin and αvβ3-integrin that promote transendothelial migration." (PMID 33870460, 2021). "Neural cell adhesion molecule L1 (L1CAM; L1CAM) is a member of the IgCAM family and was previously shown to increase melanoma migration via the MAPK pathways." (PMID 34439879, 2021). "In the melanoma cell lines, the absence of α-synuclein expression led to a significant decrease in the expression of L1 cell adhesion molecule (L1CAM) and N-cadherin, and also significantly weakened cell motility." (PMID 40860809, 2025). "Overall, these results highlight how α-syn can affect the aggressiveness of melanoma and its evolution, not only by enhancing cellular motility through the transport and trafficking of CD81, L1CAM, and N-cadherin but also by shaping the immune landscape of the tumor microenvironment." (PMID 41460324, 2025). "Using an ASO might be better than targeting L1CAM and CD81 with antibodies, as two monoclonal antibodies would have to be used, which would likely be toxic to melanoma patients." (PMID 40521809, 2025).